STUB1 (STIP1 homology and U-box containing protein 1)
Diseases named in the same sentence as STUB1 in open-access papers (continued):
Sharing a sentence is not in itself a finding about the gene and the disease.
cancer (101 papers, 2009 to 2026). A tumor composed of atypical neoplastic, often pleomorphic cells that invade other tissues. "STUB1, a functional E3 ubiquitin ligase, regulates the activity and stability of many oncogenes including stress inducible members that control cancer cell survival and progression." (PMID 40651940, 2025). "Evidence has shown that HSP70 and STUB1 play roles in multiple protein regulation in the cancer setting." (PMID 39103353, 2024). "This precise targeting mechanism leads to the degradation of MYC protein through the ubiquitin E3-ligase STUB1-mediated 26S proteasome pathway, ultimately inducing apoptosis in cancer cells and highlighting its significant role in cancer treatment." (PMID 39075086, 2024). "The biological effects of STUB1 vary across different cancers, depending on the targeting of different substrates specific to each cancer type." (PMID 39267107, 2024). "Functionally, the knockdown of STUB1 promoted cell proliferation, while the knockdown or inhibition of HSP90β significantly limited cancer progression in HCC, similar to the knockdown of YTHDF2." (PMID 37515378, 2023). "Our findings are supported by a previous study, which found that the levels of PKM2 decreased after the overexpression of STUB1 in cancer cells, which resulted in suppression of the Warburg effect." (PMID 34282188, 2021). "High glucose metabolism in cancers may be the major upstream stress for maintaining the low expression of STUB1." (PMID 40651940, 2025). "The discovery of the intersection between SUMO1 and SUMO2 modification switch of both STUB1 and KAP1 sheds new light on the regulation of EBV latency and lytic replication, which provides a potential therapeutic target against EBV-associated cancers." (PMID 32176739, 2020). "In cancer, miR-21-5p upregulation and consequent STUB1 downmodulation might have opposite effects, according to the oncogenic or tumor-suppressive effect of STUB1." (PMID 31608105, 2019). "Although the modulation of STUB1 expression in AD and cancers is controversial, it might be an interesting gene deserving to be further investigated." (PMID 31608105, 2019). "STUB1 inhibited TOP2A’s activity, reduced cancer cell proliferation, increased doxorubicin-induced apoptosis, and promoted cell cycle arrest." (PMID 41851614, 2026). "STUB1 has been reported to contribute to protein ubiquitination and degradation in cancers, and we found that FAM64A inhibited STUB1 expression; there was a direct interaction between FAM64A and STUB1 in our study." (PMID 40424038, 2025). "In certain cancers, such as colorectal cancer (CRC), glioma, and prostate cancer, STUB1 plays dual roles." (PMID 39267107, 2024). "Majority of the NRGs were deregulated in cancer tissues as compared to normal tissues which showed a uniform downregulated expression pattern except for NDRG2, BCL2, PRKN, TLR3, and STUB1." (PMID 36389725, 2022). "In this study, we used genetics screens, analysis of the Cancer Dependency Map, and IP/MS to discover a mechanism of CSF2RB regulation by a STUB1/CHIC2 complex." (PMID 36108743, 2022). "In this respect, the activity of Hsp90 in cancer cells is highly dependent on other chaperones and co-chaperones like AHA1, p23, HOP (also known as STIP1), CHIP (STUB1), Cdc37, Hsp40 and Hsp70." (PMID 30138434, 2018). "STUB1 and CHIC2 dependency scores also correlated across cell lines in the Cancer Dependency Map, suggesting that this complex may have wide ranging effects on multiple receptors." (PMID 36108743, 2022). "Activating genes in this branch, first of all TERT, heat shock protein 90 (HSP90AA1, HSP90AB1), importin 7 (IPO7) and p23 (PTGES3) are overexpressed in cancer, while the heat shock protein 70 (HSPA1A) and CHIP ubiquitin ligase (STUB1), both acting as suppressors, are underexpressed." (PMID 31750255, 2019).
cancer (continued). "The protein folding activity of chaperones is hyperactive in cancers due to enhanced interactions of phosphorylated Hsp90 with Hsp70/Hsp90-organising protein (HOP, also known as STIP1) and reduced interaction with C-terminal Hsp70 interacting protein (CHIP, also known as STUB1)." (PMID 30917858, 2019).
tumor (99 papers, 1980 to 2026). "In the present study, STUB1 was significantly downregulated in BCa tumor tissues, and low expression of STUB1 was associated with advanced progression and poor prognosis." (PMID 40651940, 2025). "The results showed that STUB1 expression was correlated with tumor location (P < 0.001), mitotic index (P < 0.001), NIH risk grade (P = 0.001), and cell morphology (P = 0.047)." (PMID 38110356, 2023). "Our data demonstrate that as a result of IFNγ-R1 stabilization, STUB1 loss leads to enhanced IFNγ response as well as to strong sensitization to cytotoxic T cell-mediated tumor cell killing in vitro." (PMID 35395848, 2022). "Whereas wildtype tumor cells moderately upregulated IFNγ-R1 expression upon treatment with increasing amounts of IFNγ, STUB1-deficient cells further elevated IFNγ-R1 protein levels, particularly the heavier, cell-surface isoforms." (PMID 35395848, 2022). "Loss of STUB1 sensitized tumour cells to IFNγ exposure and led to statistically significant enrichment of the protein targets of ISGs, including those required for antigen presentation such as H2-K1, B2M, PSME1, PSME2 and ERAP1." (PMID 35982220, 2022). "This is consistent with the observations described here, showing that STUB1-deficient tumor cells are cleared more effectively by anti-PD-1 treatment when admixed with STUB1-proficient tumor cells." (PMID 35395848, 2022). "However, in heterogeneous tumors in which wildtype tumor cells were admixed with STUB1-deficient cells, STUB1 deficiency strengthened IFNγ signaling, thereby enhancing the response to anti-PD-1 treatment." (PMID 35395848, 2022). "Finally, upon exposure to a combination of IFNγ and TNFα, loss of STUB1 further sensitized tumour cells to growth inhibition in vitro." (PMID 35982220, 2022). "In light of these results, it was important to assess whether this hyperresponsiveness to IFNγ also alters how STUB1-deficient tumor cells respond to T cell attack." (PMID 35395848, 2022). "Furthermore, STUB1 has been implicated in the modeling of the tumor immune microenvironment through its ability to regulate transcription factors that affect the secretory functions of both tumor and immune cells." (PMID 40859326, 2025). "STUB1 exhibits functional versatility across oncogenic processes—spanning tumor initiation, advancement, metastatic dissemination, chemoresistance, and clinical outcome." (PMID 41540000, 2026). "Collectively, these genetic rescue experiments demonstrated that the tumor-promoting functions of BPNT1 in TNBC are largely dependent on the STUB1-mediated ubiquitination and degradation of LIMA1." (PMID 41540000, 2026). "Identifying additional STUB1 substrates relevant to corticotroph tumor growth is an important avenue for future research." (PMID 40859326, 2025). "We then extended this observation to the in vivo xenograft tumor model derived from T24 cells after overexpression of STUB1 and found that consistent with cell culture model, STUB1 overexpression inhibited tumor growth." (PMID 40651940, 2025). "In this study, we provide evidence that STUB1 acts as a suppressor of tumor cell proliferation by controlling aspartate biosynthetic pathways through GOT2, not GOT1." (PMID 40651940, 2025). "Low STUB1 expression is associated with a poor prognosis and STUB1 overexpression suppressed BCa cell growth in vitro and vivo, suggesting that STUB1 was a tumor suppressor." (PMID 40651940, 2025). "Given that the integrated anti-tumor potency of STUB1 is enzymatically dependent, it is essential identify potential substrates, which correlated aspartate metabolism." (PMID 40651940, 2025). "Next, we sought to determine the STUB1 mRNA levels in human BCa tissues and revealed that STUB1 mRNA levels were downregulated (7/10) in BCa specimens compared with adjacent non-tumor tissues." (PMID 40651940, 2025).
tumor (continued). "We found that STUB1 overexpression dramatically decreased tumor volumes, tumor sizes and tumor weight, whereas high glucose feed can significantly rescued these effects." (PMID 40651940, 2025). "We also confirmed that STUB1 were indeed overexpressed in respective tumor tissues and the marker protein for proliferation (Ki67) in the tumor tissues of nude mice was decreased compared with control group." (PMID 40651940, 2025). "Consistently, we also determined the STUB1 protein expression in BCa tissues and paired adjacent non-tumor tissues in our center by western blotting and found that the expression of STUB1 was evidently lower in BCa." (PMID 40651940, 2025). "The results showed that STUB1 overexpression significantly inhibited xenograft tumor growth compared to the control group." (PMID 40859326, 2025). "Beyond its role in suppressing ACTH secretion via TPIT degradation, our data also demonstrates that STUB1 inhibits corticotroph tumor cell proliferation." (PMID 40859326, 2025). "We next assessed the expression of STUB1 protein in two tissue microarrays including 121 samples of BCa tissues and 34 samples of adjacent non-tumor tissues." (PMID 40651940, 2025). "Immunohistochemical analysis demonstrated that lower protein levels of STUB1 than in adjacent non-tumor tissues." (PMID 40651940, 2025). "To further confirm the results, we also performed immunohistochemical staining of GOT2 in tissue microarray, including 35 samples of BCa tissues and 34 paired adjacent non-tumor tissues, which was used to stain of STUB1." (PMID 40651940, 2025). "This was evidenced by a decrease in tumor weight and growth volume upon knockdown of STUB1 and an increase in weight and volume with overexpression of STUB1." (PMID 39267107, 2024). "Increased STUB1 expression in CCA was inversely correlated with tumor progression and overall survival." (PMID 39267107, 2024). "By promoting IFNγ signal transduction, STUB1 inhibition makes tumor cells more vulnerable to T cells." (PMID 39223632, 2024). "Conversely, the overexpression of STUB1 increased the expression of Ki67 and N-cadherin in tumor cells." (PMID 39267107, 2024). "In vivo assays revealed that reducing the expression of STUB1 hindered the growth of CCA cell xenograft tumors, whereas increasing the expression of STUB1 increased tumor growth." (PMID 39267107, 2024). "HE staining of the liver revealed that Stub1 and Uhrf1 increased the number of lesions in the tumor." (PMID 39267107, 2024). "The signaling pathway of the cytokine IFNγ in tumor cells is influenced by the E3 ubiquitin ligase STUB1." (PMID 39223632, 2024). "Knockdown of STUB1 was observed to decrease the expression of Ki67 and N-cadherin in tumor cells, as determined by an IHC assay." (PMID 39267107, 2024). "Overall, as a tumor promoter, STUB1 facilitates the proliferation, invasion, and migration of CCA cells." (PMID 39267107, 2024). "STUB1 suppresses tumor progression by ubiquitinating and degrading various substrates, including HER2, PGK1, YAP, OCT4, and EZH2." (PMID 39267107, 2024). "Three genes with gains (TORC1, MSLN, and STUB1) were selected as potential markers of the progression of a CRC tumor from HGIL to ISL." (PMID 35920319, 2023). "The results showed that STUB1 knockdown effectively blocked the anti-tumor effect of IM and reduced the promotion of lipid-ROS mediated by IM." (PMID 38110356, 2023). "Delivery of sgRNA/Cas9 RNP complexes using electroporation resulted in near complete knockout (> 99%) of STUB1 in all three tumour lines." (PMID 35982220, 2022). "Throughout our in vitro experiments, STUB1 consistently constrains the IFNγ sensing across several murine and human tumour cell lines." (PMID 35982220, 2022). "We again observed strong induction of IFNγ-R1 expression in all cell lines tested, indicating that STUB1 has a key role in limiting IFNγ-R1 expression across different tumor types." (PMID 35395848, 2022).
tumor (continued). "We observed that the tumours targeted by two independent Stub1 sgRNA were consistently more aggressive than the control tumours in mice treated with control antibody." (PMID 35982220, 2022). "Conversely, STUB1 inactivation amplifies IFNγ signaling, sensitizing tumor cells to cytotoxic T cells in vitro." (PMID 35395848, 2022). "Simultaneously, our findings highlight that a more granular understanding of IFNγ signaling (or modulation thereof) will be necessary to fully exploit the anti-tumor effects of STUB1 inhibition, in combination with ICB treatment." (PMID 35395848, 2022). "Overall, parental B16-F10 and control cells demanded at least tenfold higher concentration of IFNγ to achieve a comparable response seen in Stub1-null cells, suggesting Stub1 is a key checkpoint for IFNγ sensing in tumour cells." (PMID 35982220, 2022). "Inactivation of STUB1 increased tumour cells’ sensitivity for IFNγ, which in turn upregulated ISGs expression and enhanced antigen processing and presentation in vitro." (PMID 35982220, 2022). "We attributed these observations to the physiological role of STUB1 to downregulate the level of IFNGR1 on tumour cells’ surface, thereby reducing their ability to sense IFNγ—a key cytokine secreted by activated T cells and NK cells." (PMID 35982220, 2022). "CHIP (carboxyl terminus of HSP70‐interacting protein; also known as STUB1) is a chaperone protein and has long been described as an apoptosis inhibitor by degrading a variety of tumour‐suppressive proteins." (PMID 29493109, 2018). "Taken together, STUB1 is relatively a strong tumor suppressor in BCa cells." (PMID 40651940, 2025). "demonstrating a dominant role of STUB1- GOT2 axis in controlling of in vivo tumor growth." (PMID 40651940, 2025). "Moreover, STUB1 has been shown to modulate the expression of tumor-secreted factors, such as cytokines, growth factors, and matrix metalloproteinases, by ubiquitinating and regulating transcription factors such as CSF2RB, NF-κB, and STAT3." (PMID 40859326, 2025). "Mechanistically, UBA1 facilitates STUB1-mediated proteasomal degradation of JAK1 in tumor cells." (PMID 39540840, 2025). "As a result, STUB1 inhibitors enhance the tumor response to checkpoint immunotherapy." (PMID 39061176, 2024). "Additionally, IHC assays demonstrated that Stub1 and Uhrf1 enhanced the expression of Ki67 in tumor cells." (PMID 39267107, 2024). "In non-tumor brain tissue, both STUB1 and SVIP were expressed in similar regions." (PMID 39138166, 2024). "In the mouse primary CCA model, the overexpression of Stub1 and Uhrf1 individually promoted tumor progression, whereas the combined overexpression of both Stub1 and Uhrf1 further enhanced tumor progression, as demonstrated by the higher liver weight-to-body weight ratios observed in each group." (PMID 39267107, 2024). "Overall, TORC1 and MSLN may be candidate markers predicting the progression from HGIL to ISL28, 31, 32 and STUB1 was reported to act as a tumor suppressor." (PMID 35920319, 2023). "STUB1, which is a co‐chaperone protein and U‐box‐containing E3 ligase, is involved in the degradation of several oncogenic proteins, including ErbB2, hypoxia inducible factor 1α, and c‐Myc, and consequently acts as a tumor suppressor." (PMID 35920319, 2023). "In addition, in vivo assay showed that overexpression of YTHDF2 rescued the tumor suppression induced by the HSP90β‐KD or overexpression of STUB1 in HepG2 xenografts." (PMID 37515378, 2023). "However, it should be noted that our investigations were limited to probing the role of STUB1 in syngeneic tumour cells." (PMID 35982220, 2022). "Interestingly, STUB1 is enriched in M0 and M2 macrophage, compared to M1 macrophage, across most of the tumour types." (PMID 35982220, 2022). "Next, we asked if inactivation of STUB1 could sensitize human tumour cells to growth inhibition induced by the cytokines such as IFNγ and TNFα." (PMID 35982220, 2022).
tumor (continued). "To understand if inactivation of Stub1 could sensitize tumours to immunotherapy, we inoculated the CRISPR-edited B16-F10 clonal cells into immuno-competent C57BL/6 J mice." (PMID 35982220, 2022). "Emerging evidence points to a role for STUB1 in tumour immune evasion and anti-PD-1 resistance." (PMID 35982220, 2022). "Finally, we compared STUB1 expression in tumours and adjacent normal tissues across multiple tumour types for which the data are available in TCGA." (PMID 35982220, 2022). "Other biological pathways regulated by STUB1 might oppose and negate the anti-tumour immunity in a complex tumour microenvironment." (PMID 35982220, 2022). "Recent studies have highlighted the involvement of STUB1 in various human malignancies, as it regulates the stability and activity of several tumor-associated transcription factors, such as CRIP1, YAP1, HIF-1α, and c-Myc, thereby influencing tumor growth, invasion, metastasis, and angiogenesis." (PMID 40859326, 2025). "Sanguinarine (SAG) could reduce the protein stability of GPX4 via E3 ligase STUB1-induced ubiquitination and degradation of GPX4, then increase ROS, MDA, and Fe2+ levels, and finally cause the ferroptosis of NSCLCs and suppress tumor growth and metastasis in vivo." (PMID 38247539, 2024). "Thus, we hypothesized that inactivation of STUB1 may reverse ICB resistance by increasing tumour cells’ sensitivity for IFNγ." (PMID 35982220, 2022). "Collectively, these findings delineate a novel oncogenic axis wherein BPNT1 scaffolds STUB1-mediated ubiquitination and degradation of LIMA1, driving EMT-facilitated tumor progression and DTX chemoresistance." (PMID 41540000, 2026). "Our findings position BPNT1 as a novel molecular scaffold that redirects STUB1’s catalytic activity toward LIMA1 degradation, resolving its tumor-promoting role in TNBC." (PMID 41540000, 2026). "Collectively, these data demonstrate that BPNT1 scaffolds STUB1 recruitment to catalyze ubiquitin-dependent proteasomal degradation of LIMA1, thereby depleting this tumor suppressor in TNBC." (PMID 41540000, 2026). "Our study reveals a novel mechanism in which USP20 competitively interacts with STUB1 to stabilize CTSL and promote tumour progression." (PMID 41261048, 2025). "Taken together, STUB1 appears to be a strong suppressor, whereas GOT2 is a tumor oncogenic protein in BCa cells." (PMID 40651940, 2025). "Downregulation of FAM64A inhibited tumor growth and lung metastasis in mice, possibly by suppressing TWIST1 ubiquitination and degradation via the E3 ubiquitin ligase STUB1 and activating the Wnt/β-catenin signaling pathway." (PMID 40424038, 2025). "We also confirmed that STUB1 or GOT2 were indeed overexpressed or knocked down and STUB1 overexpression increased GOT2 expression in respective tumor tissues." (PMID 40651940, 2025). "Mechanically, DAB2IP interacted with the E3 ubiquitin ligase STUB1 via its PER domain, thus triggering STUB1 mediated HIF-1α ubiquitylation and degradation, and inhibit glucose metabolism and tumor progression." (PMID 38862467, 2024). "High IGFBP-2 level was related to rapid tumor growth and shorter survival time indicating low expression of SVIP and high expression of STUB1 in GBM cells." (PMID 39138166, 2024). "STUB1/CHIP (STIP1 homology and U-box containing protein 1/C-terminal Hsp-interacting protein) levels were higher in lymph nodes than in paired primary tumours." (PMID 32429269, 2020). "The resulting analysis showed that STUB1 is slightly depleted in tumours associated with high GEP score (top 55th percentile, GEPhi) regardless of the TMB value, suggesting low STUB1 correlates with inflamed tumour microenvironment." (PMID 35982220, 2022). "Taken together, we propose a framework whereby STUB1 may confer ICB resistance by downregulating IFNGR1 on the cell surface, thus curbing the tumour cells’ ability to sense and respond to IFNγ." (PMID 35982220, 2022).